INS (insulin)
Diseases named in the same sentence as INS in open-access papers (continued):
Sharing a sentence is not in itself a finding about the gene and the disease.
diabetes (continued). "Diabetes is a chronic disease characterized by elevated blood glucose levels, resulting from insufficient insulin production by the pancreas or insulin resistance in peripheral tissues (Classification and Diagnosis of Diabetes, 2019)." (PMID 41306918, 2025). "An animal develops diabetes due to the combination of insulin resistance and the reduced production of this hormone." (PMID 40426986, 2025). "Diabetes mellitus (DM) is a chronic endocrine disorder characterized by elevated blood glucose levels resulting from either insufficient insulin secretion, insulin resistance, or a combination of both factors." (PMID 39851597, 2025). "Type 2 diabetes mellitus is a heterogenous set of disorders marked by varying levels of insulin resistance, impaired insulin secretion, and enhanced hepatic glucose production." (PMID 40260359, 2025). "Animal studies indicate that higher vegetable intake helps to reduce body weight, plasma glucose, and insulin resistance, thereby contributing to the regulation of glucose–insulin homeostasis and diabetes prevention." (PMID 38747471, 2025). "By promoting glucose metabolism and improving insulin sensitivity, these compounds can effectively improve blood sugar levels, aiding in the prevention and treatment of diabetes." (PMID 40298838, 2025). "Meta-analyses of diabetes cognitive impairment models indicate berberine improves fasting blood glucose and memory function, likely through mechanisms involving insulin resistance improvement, anti-oxidant and anti-neuroinflammation." (PMID 41378215, 2025). "Significant advances have been made in diabetes monitoring and insulin delivery technologies in recent years that have substantially optimized blood glucose management for elderly patients with diabetes." (PMID 41180388, 2025). "In the context of implanted devices for cell therapies, such as the use of islets in type 1 diabetes mellitus, diffusion time of glucose from the bloodstream to the islets, and of insulin from the islets to the bloodstream, is of critical importance." (PMID 39692747, 2025). "Leflunomide, a drug used in the treatment of rheumatoid arthritis, shows potential in diabetes therapy by enhancing insulin sensitivity and reducing hyperglycemia in mice." (PMID 41440753, 2025). "Diabetes mellitus (DM) is a chronic metabolic disorder characterized by persistent hyperglycemia due to insufficient insulin production or impaired insulin action." (PMID 40151690, 2025). "The precise diagnosis of diabetes has enabled the replacement of unnecessary insulin injections with oral medications or lifestyle adjustments in our patients and their adult family members." (PMID 39504571, 2025). "The continued evolution of insulin therapy represents one of medicine’s greatest success stories, with future innovations promising even greater improvements in diabetes care and patient outcomes." (PMID 41531706, 2025). "Non‐fasting (stimulated and random) serum C‐peptide values ranging from 500–970 pmol/L distinguished between insulin‐requiring and non‐insulin‐requiring diabetes." (PMID 39797595, 2025). "Type 1 diabetes mellitus (T1DM) stands as a chronic autoimmune disorder characterized by the immune‐mediated destruction of pancreatic β cells responsible for insulin production." (PMID 39873909, 2025). "We then performed GO and KEGG analysis on the differentially expressed genes in m6A modification sites before and after intensive insulin therapy in people with diabetes." (PMID 40299682, 2025). "Diabetes mellitus type 2 (T2DM), which represents around 90% of diabetes, is a long-term, chronic, persistent metabolic disorder characterized by hyperglycemia due to the body’s inability to regulate blood sugar levels of insulin." (PMID 39758866, 2025).
diabetes (continued). "In countries like Iraq, ongoing systemic barriers, ranging from economic instability and limited healthcare infrastructure to regional conflict and disrupted insulin supply chains, compound the difficulties of managing chronic conditions like diabetes." (PMID 40755641, 2025). "The term “type 3 diabetes” results from a conjunction of the pathological mechanisms observed in diabetes and Alzheimer’s disease, primarily insulin resistance, persistent hyperglycemia, and cognitive deficits." (PMID 41009376, 2025). "In summary, the QWINT programme is a comprehensive series of trials designed to evaluate the potential of efsitora alfa as a once-weekly insulin treatment for people with diabetes." (PMID 39810242, 2025). "Some reports suggest that metformin exerts neuroprotective properties, potentially mitigating diabetes-related cognitive decline by modulating inflammation, promoting neurogenesis, and enhancing insulin signaling in the brain." (PMID 40004246, 2025). "The induction of diabetes through alloxan administration occurs due to the selective destruction of pancreatic β‐cells, which are responsible for insulin production." (PMID 40548186, 2025). "Due to the nature of the disease, diabetes involves a large degree of data collection and self-care in order to accurately administer insulin and avoid these hyper- and hypoevents." (PMID 40424579, 2025). "The German Diabetes Study (GDS) monitors whole-body insulin sensitivity using euglycemic–hyperinsulinemic clamps in people with recent onset diabetes every 5 years for up to 20 years." (PMID 39998445, 2025). "Diabetes is a chronic metabolic disease characterized by abnormally high blood glucose levels due to insufficient insulin secretion by pancreatic cells and/or resistance to the antidiabetic hormone, insulin." (PMID 40590050, 2025). "Diabetes mellitus (DM) is a chronic metabolic disorder characterized by persistently high blood sugar levels resulting from insufficient insulin production, insulin resistance, or both." (PMID 40873447, 2025). "Conventionally, insulin therapy has been the favoured treatment option, with only limited evidence of safety data available on non-insulin-based diabetes medications from the perspective of fetal development." (PMID 39993530, 2025). "As diabetes management increasingly relies on digital tools—such as continuous glucose monitoring, insulin pumps, and app-based decision aids—it becomes crucial to understand how patients experience and adapt to these technologies." (PMID 41302228, 2025). "This study aimed to shed light on the recent advances in Au-nanostructured-based biosensors in detecting glucose and other diabetes biomarkers, such as HbA1c, GA insulin, IAA, and GADA." (PMID 39355278, 2024). "Mitochondrial dysfunction is related to the pathophysiology of diabetes, resulting in impaired ATP production and defective insulin secretion." (PMID 38891081, 2024). "In the unmatched samples of the baseline characteristics, significant between group differences were observed in dyslipidemia, diabetes mellitus, heart failure, and ejection fraction < 50%, aspirin, thienopyridine, cilostazol, statin, and insulin." (PMID 39044873, 2024). "A case–control research indicated that pathological iron overload played a direct role in the pathogenesis of β-cell failure and insulin secretion in diabetes." (PMID 39430450, 2024). "It is widely believed that diabetes induces ovarian cancer by releasing excessive insulin and disturbing the balance of sex hormones." (PMID 38378582, 2024). "Insulin, as well as diabetes management devices and related supplies like test strips, are not currently covered." (PMID 39262683, 2024). "The interplay between diabetes mellitus and osteoporosis is complex, often involving hyperglycemia’s adverse effects on bone health and insulin’s role in bone metabolism." (PMID 38451994, 2024).
diabetes (continued). "The occurrence of hypoglycemia is notably frequent among diabetic individuals undergoing insulin or sulphonylurea therapy, representing a primary challenge in managing diabetes mellitus." (PMID 39004753, 2024). "Drugs based on peptides and proteins (PPs) have been widely used in medicine, beginning with insulin therapy in patients with diabetes mellitus over a century ago." (PMID 38255888, 2024). "The prevalence of insulin injections as the primary treatment method (98.5%) observed in our study underscores the pivotal role of insulin therapy in effectively managing diabetes in our study population." (PMID 39539431, 2024). "A small number of adolescents or adults used hypoglycemic drugs (mainly metformin) in the early stage of diabetes, and then gradually changed to insulin." (PMID 37204622, 2024). "Of these, 5228 (14%) had obesity (BMI ≥ 30 kg/m2), 1415 (4%) had diabetes (requiring treatment with insulin or oral hypoglycemics), and 688 (2%) had obesity + diabetes pre-transplantation." (PMID 38062242, 2024). "Since the discovery of insulin over 100 years ago, there have been a lot of advances in the treatment of diabetes." (PMID 39429740, 2024). "“One thing which annoys me is when doctors provide conflict information; I go to one doctor and he tells me that I have to take tablet for my diabetes, I go to another doctor and he tells me to take insulin injection." (PMID 39232660, 2024). "Diabetes often results from insufficient insulin production by the pancreas or an inadequate cellular response to the insulin produced." (PMID 38957825, 2024). "For instance, Hddc3 and Zfp69, whose expression is downregulated under light conditions, are involved in ferroptosis and insulin sensitivity during diabetes, respectively." (PMID 38252153, 2024). "While our study did not delve deeply into the differential impact of glycemic control on gastric function between insulin-dependent and insulin-independent diabetes, we did explore the relationship between controlled blood glucose levels and gastric symptoms." (PMID 39664090, 2024). "Various diets aimed at weight reduction and improving insulin sensitivity are advocated for patients with diabetes, among them high-protein diets." (PMID 39114126, 2024). "Weight cycling increases the incidence of diabetes by impairing the function of β cells, up-regulating or down-regulating the expression of insulin-secreting genes, and β-cell endoplasmic reticulum stress." (PMID 38921478, 2024). "Diabetes is characterized by long term hyperglycaemia due to abnormalities in either insulin secretion, insulin function, or both." (PMID 39456447, 2024). "Whilst the supply of oral diabetes medications was relatively acceptable at the time, insulin supply was erratic." (PMID 38768080, 2024). "Diabetes mellitus (DM), a disorder of the carbohydrate, lipid, and protein metabolism characterized by hyperglycemia and dysfunctional insulin secretion or action, has become a major global health crisis." (PMID 39458839, 2024). "Type 2 diabetes mellitus (T2DM) is a serious metabolic disease characterized by insulin resistance and reduced insulin production, which causes abnormally elevated blood glucose." (PMID 38560269, 2024). "Although improving insulin signaling is key to reversing diabetes, the multi-organ mechanisms regulating this process are poorly defined." (PMID 39033139, 2024). "Diabetes mellitus is a disorder that occurs due to the defective pancreatic secretion of insulin or insulin resistance." (PMID 39795285, 2024). "For example, 36.5% believe that serious side effects can show up due to a prolonged use of oral hypoglycemic drugs and insulin, and 31% people with diabetes can eat anything they want if they take the medication." (PMID 38525337, 2024). "The research problem involves finding the best means of presenting young people with personalized guidance on insulin dosing and carbohydrate intake strategies for facilitating diabetes management around exercise." (PMID 39078700, 2024).
diabetes (continued). "Type 2 diabetes mellitus (T2DM) is a common form of diabetes described as hyperglycemia resulting from insulin resistance or insufficient insulin secretion by pancreatic β-cells." (PMID 39064870, 2024). "An important one is insufficient knowledge of insulin and diabetes management on the part of healthcare providers and patients, leading to errors in insulin therapy." (PMID 38594659, 2024). "Given the critical role of adipocytes in glucose metabolism, M. oleifera extracts show promising applications in diabetes management by potentially enhancing insulin sensitivity, regulating lipid metabolism, and improving overall metabolic function." (PMID 39458951, 2024). "Use of sodium-glucose cotransporter-2 (SGLT2) inhibitors (13.2% versus 43.2%), glucagon-like peptide-1 receptor agonists (GLP1-RAs) (1.0% versus 6.2%), and insulin (27.7% versus 58.1%) were lower in General medicine than in Diabetes specialist clinics." (PMID 38166049, 2024). "Diabetes is a persistent medical condition characterized by elevated levels of sugar in the blood due to insufficient production of insulin or ineffective absorption of insulin by cells." (PMID 39416696, 2024). "Medications currently available for treatment of diabetes mellitus include insulin and numerous antidiabetic molecules, such as thiazolidinediones, sulfonylureas, metformin and glinides." (PMID 39683116, 2024). "We suggest that glutamine in insulin is an important scavenger to prevent hyperoxidation, as glutamine has antioxidant capacity in Diabetes, and supplementation reduces oxidative stress." (PMID 39378614, 2024). "Balanced food intake with endogenous and/or exogenous insulin levels is the most important for diabetes treatment in improving glycemic control." (PMID 39995445, 2024). "Diabetes-induced rats exhibited a reduction in blood insulin and HOMA-β, whereas the FBG and HOMA-IR increased." (PMID 38982468, 2024). "The same group extended their observation and retrospectively analyzed 60 PD patients with diabetes treated with insulin." (PMID 37989976, 2024). "Type 2 diabetes mellitus is a metabolic disease characterized by high blood glucose that results from a decrease in insulin or tissue resistance to insulin." (PMID 38481202, 2024). "It is known that STZ diabetes model leads to impairment of the ß-cells of the pancreas, leading to decreased synthesis and release of insulin into circulation." (PMID 38324798, 2024). "The minimum standards for treatment of diabetes in Malawi recommend the availability of at least Metformin, Glibenclamide and Insulin at health centers." (PMID 38771783, 2024). "In the female subpopulation of insulin-treated diabetes, HPLBII-P was raised (p = 0.02) as compared to women treated with oral antidiabetics only." (PMID 38731158, 2024). "miRNA-155 regulates insulin sensitivity, and its dysregulation contributes to developing diabetes mellitus complications." (PMID 38674437, 2024). "Diabetes mellitus is a chronic metabolic disorder characterized by elevated blood glucose levels resulting from impaired insulin secretion, insulin action, or both." (PMID 38475848, 2024). "Both quercetin and luteolin have been shown to enhance glucose tolerance and insulin sensitivity in diabetes studies." (PMID 39568571, 2024). "This often leads to behaviors such as intentionally neglecting diabetes management in social contexts, including the deliberate omission of insulin dosing, glycemic monitoring, or carbohydrate counting." (PMID 38338194, 2024). "Historically, most patients with type 1 diabetes mellitus had a bad perception of their future health before insulin treatment was introduced." (PMID 39797147, 2024). "As the duration of diabetes increases, fewer people remain positive for diabetes autoantibodies other than anti-insulin antibodies." (PMID 39247917, 2024).
diabetes (continued). "Flavonoids are part of the class of nutraceuticals that have been demonstrated to improve insulin sensitivity, manage hyperglycemia in diabetics, and govern metabolism." (PMID 39493778, 2024). "Previous studies have demonstrated that imatinib improves insulin signalling by reducing JNK activity in patients with diabetes mellitus." (PMID 38424569, 2024). "The treatment of diabetes typically involves the use of insulin, oral hypoglycemic agents, or incretin-based therapies." (PMID 39771551, 2024). "The most common disorder of glycogen metabolism is observed in diabetes, in which abnormal amounts of insulin or abnormal insulin response result in accumulation or depletion of liver glycogen." (PMID 39199279, 2024). "Breaking this vicious cycle between obesity and diabetes requires integrated interventions targeting weight management, glycemic control, and insulin sensitivity." (PMID 38800249, 2024). "This study aligns with research that identified the association of nsSNPs with diabetes mellitus, and research emphasized the relevance of genetic changes in the INS gene in the development of diabetes mellitus." (PMID 38673052, 2024). "Healthy mice were injected with streptozotocin to induce type 1 diabetes (as indicated by pronounced hyperglycemia, greater >250 mg/dL) and a subset was subsequently treated with a subcutaneous insulin pump up to 8 weeks after the induction of diabetes." (PMID 38786744, 2024). "This type of diabetes mellitus (DM) is described by insufficient pancreatic beta-cell performance to meet the increased insulin need due to pregnancy." (PMID 38617398, 2024). "These were apoptosis, insulin signaling pathways, leukocyte endothelial migration, and type 1 diabetes mellitus, confirming the results obtained by GO analysis." (PMID 38791576, 2024). "Like humans, cats have a strong relationship between decreasing insulin sensitivity and the development of diabetes with obesity." (PMID 39684905, 2024). "A progressive decrease in the prescription of sulphonylureas and concomitant increase of innovative drugs was registered in the third quinquennium among those starting basal insulin, although with rates still far from those recommended by diabetes guidelines." (PMID 38441838, 2024). "Insulin was the most common initial therapy for diabetes (n = 89/95) with one patient also using SU (glimepiride), and 6 not receiving any antidiabetic therapy prior to thiamine therapy." (PMID 39025920, 2024). "Technological support can be crucial for T1D self-management routines of AYAs, with context-aware diabetes technology like hybrid closed-loop (HCL) insulin pump systems playing a pivotal role." (PMID 38846748, 2024). "The resulting insulin-producing cells can control chemically induced diabetes in rodents and were the subject of several clinical trials." (PMID 38281991, 2024). "It is well-known that changes in amino acid metabolism play a key role in the pathogenesis of insulin dysfunction and diabetes." (PMID 39687851, 2024). "Toxicity cases involving CAM therapies in individuals with diabetes highlight potential dangers, including renal failure with chromium picolinate and unsatisfactory outcomes after discontinuing insulin injections for alternative therapies." (PMID 38978922, 2024). "For instance, when junior staff were caring for patients with diabetes and complex issues, an insulin management App provided guidance." (PMID 38145375, 2024). "Diabetes mellitus (DM) is a lasting condition impacting metabolism, either due to defective insulin secretion or peripheral organ resistance to insulin, characterized by elevated blood sugar levels." (PMID 39099905, 2024). "For self-care, there was a score worsening in patients with longer duration of diabetes [OR 1.1 (1.0-1.1)] and in those using insulin [OR 8.3 (1.7-41.4); rpb 0.23, P = 0.01]." (PMID 39420900, 2024).